IL17A (interleukin 17A)
Diseases named in the same sentence as IL17A in open-access papers (continued):
Sharing a sentence is not in itself a finding about the gene and the disease.
infection (continued). "We detected an increasing number of YFP+ cells in the course of infection and in particular IL-17A-producing and IFN-γ-producing cells expanded over time, indicating that Th17 cells become more flexible during infection and show plasticity towards a Th1 cell phenotype." (PMID 35446923, 2022). "Compared to infection with P. aeruginosa PAO1 alone, infection with P. aeruginosa PAO1 combined with AI-2 treatment resulted in significantly increased levels of IL-17A, numbers of Th17 cells and levels of STAT3 in the lung tissues of WT mice (P < 0.05), as well as more serious lung damage." (PMID 36033859, 2022). "When infected with an elevated dose of Mtb, however, IL-17A−/− mice exhibited significantly enhanced bacterial loads at later but not at earlier time points of infection (right)." (PMID 36139450, 2022). "The IL-17A level was significantly increased in all three infection groups compared to the mock-infected group, without a significant difference among the infection groups." (PMID 35281073, 2022). "Our results revealed that IL-10, IL-8, IL-6, IFN-, IL-17A, and IL-17F levels in patients with bacterial lung illness were abnormally higher than those without infection." (PMID 36319826, 2022). "Therefore, we initially examined the effects of a high-dose Mtb infection by analyzing the outcomes of infection in C57BL/6 and IL-17A−/− mice." (PMID 36139450, 2022). "The concentration of the cytokines TNF-α and IFN-γ (Th1) was higher in the infected animals (p < 0.05) compared to the controls (without infection), and this increase was much more marked in the Il17a−/− mice than in wild C57BL/6J mice (infected)." (PMID 35208830, 2022). "Thus, after infection with the Mtb isolate HN878, a pronounced induction of IL-17A correlates with an impact of the cytokine for early protective immune responses against the hypervirulent Mtb strain." (PMID 36139450, 2022). "In accordance with the higher mycobacterial load, in the absence of IL-17A, infection with an elevated dose of Mtb H37rv results in the presence of larger inflammatory infiltrates in the lungs." (PMID 36139450, 2022). "The response of intracellular IFN-γ, IL-17A, and IL-21 expressing CD4+ or CD8+ effector T cells in HBV resolved infection was significantly higher than observed in OBI or CHB (P < 0.05), while the concentration of circulating IL-17A was higher in OBI and CHB (P < 0.01)." (PMID 35464946, 2022). "Together, these results clearly demonstrate that in the absence of IL-17A, the infiltration of neutrophils is exacerbated after infection with a high dose of Mtb H37rv." (PMID 36139450, 2022). "Following stimulation, splenocytes were discovered to overexpress IL-17A, which has been hypothesized to produce CD4+ cells that occupy the lung post-infection and produce chemokines that recruit IFN-γ secreting CD4+ T cells to help control the infection." (PMID 35482149, 2022). "In contrast, in IL-17A−/− mice, bacterial containment and protective immune responses to infection with ~ 100 CFU Mtb H37RV are not altered." (PMID 36139450, 2022). "In conclusion, our results surprisingly show that after experimental infection with high doses of Mtb H37rv, the absence of IL-17A provoked a strong accumulation of Mtb-containing neutrophils in the lung, which triggered susceptibility to Mtb." (PMID 36139450, 2022). "For example, mice lacking IL-17a had decreased neutrophil influx following infection with several strains of Spn, but had strain-dependent correlation with mouse survival." (PMID 35646729, 2022). "The present study demonstrated that after high-dose infection with Mtb H37rv, the absence of IL-17A results in the accumulation of neutrophils within the centers of clearly pronounced inflammatory lesions." (PMID 36139450, 2022).
infection (continued). "Although the pathogenesis of VU is likely multi-factorial, our results indicate that the increase of specific inflammatory mediators, such as IL-6, IL-10, IL17A, and TNF-α in wound fluids can be found in the presence of an infection particularly when sustained by biofilm-producing bacteria." (PMID 36140047, 2022). "Interestingly, a population of IL-17A and IFN-γ co-producing CD4+ T cells emerged in the kidney after infection." (PMID 35446923, 2022). "In CLN, there were also elevated numbers and percentages of IL-17A-producing ILC3 cells in IL10-/- mice on day three but not day five after infection." (PMID 36016413, 2022). "Histological analysis was performed to assess bone healing and infection; however, we did not observe any major differences between wild-type (WT) and IL-17A KO animals with that approach." (PMID 34240122, 2021). "In contrast, in the infected control group, IL-2, IL-4, IL-6, and IL-17a levels rose slowly and did not change significantly after day 21 post-infection." (PMID 33717108, 2021). "We had previously shown that Il17A−/− mice have enhanced bacterial load in the lungs, and consistent with this, we found that the CFU counts were higher in the lungs of Il17A−/− compared with wild type (WT) mice throughout the course of infection." (PMID 33976385, 2021). "Antigen processing is not required for γδ T cells to recognize an infection, since γδ T cells can quickly react to various antigens via innate surface receptors and secret high levels of IL-17A and IFN-γ, both are signature cytokines of γδ T cells." (PMID 33995408, 2021). "The absence of IL-17A had a less obvious effect on neutrophil recruitment or the course of infection in the lungs." (PMID 33976385, 2021). "As expected, since S. tm induces inflammation mainly in the cecum in vivo, IL-17A production from CD3+CD4+ small intestinal LPLs was not altered after infection with S. tm.." (PMID 34566952, 2021). "Nevertheless, although IL-17A did neither affect the early expression of CXCR3 chemokines nor vaccine-induced protection in the early phase of infection with Mtb, the induction of antigen-specific Th1 cells after vaccination appeared to be dependent on IL-17A." (PMID 34351501, 2021). "Similar to those in wild-type mice, bacterial burdens in unvaccinated and vaccinated IL-17A−/− mice were not yet significantly different at week 2 post-infection, while vaccination led to significantly reduced bacterial loads at week 3 and 6 post-infection." (PMID 34351501, 2021). "For example, infection-induced levels of TNF-α, IL-1β, and IL-17A were higher in the sera of pregnant mice than in the sera of virgin control mice, which parallels their increased bacterial burden, whereas the anti-inflammatory cytokine IL-10 peaked to higher levels in virgin than in pregnant mice." (PMID 33622714, 2021). "Mice, which have been infected once but not reinfected, served as a control group for the secondary infection and exhibited reduced Trm17 responses in terms of IL-17A production and overall CD4+ T cell frequencies." (PMID 33595670, 2021). "Given that plasma cells support the majority of MHV68 reactivation from wild-type splenocytes and ubiquitous expression of IL-17RA, these data suggest that IL17A proviral effects on MHV68 infection are not restricted to a single cell type." (PMID 33824206, 2021). "Once again, some WT animals (25%) had cleared the infection by day 14, although none of the IL-17A KO animals cleared the infection at that time point." (PMID 34240122, 2021). "To address whether IL-17A controls IL33-mediated immunopathology in our model, we applied IL-17A to IL-33-treated CR-infected mice from day 3 post infection on and characterized disease progression." (PMID 33654214, 2021). "Il17A−/− and WT mice were aerosol challenged with B. pertussis left for 6 months (when they cleared the infection; data not shown) and then re-challenged by aerosol with B. pertussis." (PMID 33976385, 2021).
infection (continued). "We observed that the deletion of the cryptococcal VLP1 gene did not affect the production of cytokines such as IL-2, INF-γ, Il-17A, and IL-18 in host blood in the early, middle, and late stages of infection." (PMID 34072011, 2021). "At week 2 post-infection, expression levels of Cxcl10 and Cxcl11 tended to be higher in vaccinated C57BL/6 and IL-23p19−/− mice and were even significantly increased in vaccinated IL-17A−/− mice when compared to the respective unvaccinated control group." (PMID 34351501, 2021). "Frequencies of STM-specific IFN-γ, TNF-α and/or IL-17A-producing T cells measured in these tissues at 7 and 21 days post Salmoporc vaccination and/or STM infection were then compared between only vaccinated (VAC), vaccinated and infected (V+I), only infected (INF) and untreated control (CON) pigs." (PMID 34451970, 2021). "Along with this observation, we also observed significantly lower levels of IL-6, IFN-γ, and CXCL-10 24 h post-infection, IL-17A and TNF-α 4 days post-infection, and IL-1β, CCL2 and CCL5 7 days post-infection in the lung of IL-38-treated mice, compared with mice without IL-38 administration." (PMID 33414457, 2021). "In contrast, we did not see substantial accumulation of IL-17A+ ILCs in infected groups at the peak of infection (5 weeks) with only a modest increase in S. epidermidis colonized and L. major infected mice compare to L. major alone in the skin." (PMID 34699567, 2021). "We subsequently performed an overexpression assay of IL17A in PK15 cells, and then inoculated with GS2018 at a multiplicity of infection (MOI) of 1.0, which showed significant increase in IL17A (p < 0.01) at 24, 48 and 72 h after infection." (PMID 34872498, 2021). "Nevertheless, administration of IL-17A during CR infection was not sufficient to rescue the severe immunopathology." (PMID 33654214, 2021). "By analysing cytokines associated with the major CD4+ve Thelper (Th) cell subsets (Interferon-gamma (IFN-γ)/Th1; Interleukin (IL)-4/Th2; IL-17A/Th17; IL-10/Tregulatory), we show that there is selective activation of PBMC producing IFN-γ and/or IL-10 during the latent phase following infection." (PMID 32487248, 2020). "The magnitude of IL-17A production following exposure to chlamydial antigens was much lower than those to ConA, irrespective of the infection group." (PMID 32487248, 2020). "Whilst the current study did not examine these particular components of the immune system, infection of the co-culture model in the presence of CM from PBMCs already primed by BCG showed no significant further increase in either IL17a or IL22." (PMID 33116165, 2020). "Previous analyses of MAP whole cell lysate stimulated immune responses at 6–15 months post-infection have consistently identified one or more of IFNG, IL12, TNFA, and/or IL17A (either transcript or protein) as up-regulated in either CPPs or the draining MLN cells." (PMID 32547548, 2020). "Strikingly, by d7pi, IL-5+ and IL-13+ CD4+ T cell numbers did not increase in Il17a-KO mice in response to infection." (PMID 32636457, 2020). "IL-17A is capable of recruiting neutrophils but also induces neutrophilia and neutrophils are not exclusively protective of infections." (PMID 32477272, 2020). "The expression level of IL-17A did not significantly change after infection, which is consistent with the trend of the changes in Th17 cells." (PMID 33180882, 2020). "During infection with Mtb, the major TH17 cytokine IL-17A mediates the formation of granuloma via chemokine induction and the accumulation of a protective TH1 immune response, but on the other hand, it contributes to the early neutrophil-dependent inflammation." (PMID 33375150, 2020). "A considerable increase of IL-17A+ γδ T cells was detected in the lungs upon infection, that was however not different between vaccinated and control mouse groups." (PMID 32040500, 2020).
infection (continued). "ILC2s displayed a similar pattern, as cell numbers significantly increased with infection in WT but not in Il17a-KO mice." (PMID 32636457, 2020). "The cytokine IL-17A has the function of inducing granulopoiesis, inflammatory response, recruiting neutrophils, inducing fungicidal activity, inducing microbial peptides such as S100A7, S100A8, and promotion of resistance to infection." (PMID 33302372, 2020). "To study which factor is related to reduced fibrosis in S. japonicum-infected TCR δ KO mice, we extracted RNA from the liver tissue of the WT and KO mice at 6 weeks post-infection, and measured the mRNA transcripts of collagen, TGF-β, IL-17A and IL-13 using qRT-PCR." (PMID 32611373, 2020). "In line with this in our study, Type-1 (IFN-γ, TNF-α, and IL-2)- and Type-17 (IL-17A)- cytokines were significantly decreased in INF individuals when compared to those without Ss infection." (PMID 33042134, 2020). "Estrogen pre-treatment of VK2 E6/E7 cells did not enhance these IL-17A effects, but synergistic effects were suggested when mimicking infection through the use of flagellin." (PMID 32439855, 2020). "Subsequently, we sought to examine the influence of Ss infection on the systemic levels of Type-1 (IFN-γ, TNF-α, and IL-2), Type-17 (IL-17A and IL-22), Type-2 (IL-4, IL-5, and IL-13), regulatory (IL-10) and pro-inflammatory cytokines (IL-1α, IL-1β, IL-6, IL-12, and GM-CSF) in INF and UN individuals." (PMID 33042134, 2020). "We observed that higher IL‐17A, IL‐10 and sE‐selectin levels identify patients with IE infection foci (diagnosed by TEE or TTE imaging) when compared to extravascular infections, while the other five biomarkers, available risk factors or clinical data did not (P > 0.05, data not shown)." (PMID 32082571, 2020). "Many studies demonstrated the important protective role of IFN-γ, nitrite, IL-17A, MIF, TNF and IL-6 during infection by T. gondii." (PMID 30809216, 2019). "One of our hypotheses associated to a direct role of IL17F in TB, implies that different amounts of this cytokine could influence the levels of IL17A and IFNG secreted by HD and TB, affecting the onset of the infection." (PMID 31616423, 2019). "In the present study, IL-17A transcript levels also significantly increased with age, even in the absence of infection." (PMID 31222079, 2019). "But in the oral L. monocytogenes infection model, intestinal multifunctional γδ+T cells able to simultaneously produce IFNγ and IL-17A can provide enhanced protection against infection and even compensate for the absence of αβ+T cells." (PMID 31354728, 2019). "IL-10 levels decreased (albeit not significantly) at 6 h and 30 h after infection, and increased significantly at 3–6 dpi, and IL-17A levels decreased significantly at 6 dpi, and significantly increased at 30 h and 3 dpi." (PMID 31855175, 2019). "Interestingly, the expression levels of all genes were dramatically decreased in the IL-17A knock-out mice, as compared to the WT mice, after PR8 infection." (PMID 31681209, 2019). "NK cells stimulated by IL-12 or IL-18, secreted from dendritic cells and macrophages, produce several cytokines, principally IFN-γ, IL-1β, IL-8, IL-17A, and tumor necrosis factor alpha (TNF-α), which are involved in lung inflammatory processes and infection resistance." (PMID 31269777, 2019). "This was confirmed by clinical data in MV patients, where two days of mechanical ventilation, in the absence of any infection, led to a significant increase in IL-17A levels in ETA, compared to the pre-ventilation timepoint levels." (PMID 31614857, 2019). "Although a transient induction of IFN-γ+IL-17A+ Th17 cells was observed in SFB colonized mice at 2 weeks after infection, the proportion of IFN-γ+IL-17A− Th17 cells was significantly higher in C. rodentium colonized mice than in SFB colonized mice at all time points." (PMID 31229354, 2019).
infection (continued). "We also looked at the inflammatory cytokines IL-6, IL-17A and IL-23: IL-6 was expressed in the ganglion cell layer following infection with the PRU parental and mutant strains, but absent with RH parental and knock-out strains." (PMID 30901349, 2019). "Our previous study described that co-infected Ss infection with active or latent TB has significantly reduced Type 1 (IFN-γ, TNF-α, and IL-2), Type 17 (IL-17A and IL-17F) and increased regulatory as well as Type 2 (IL-4, IL-5, and IL-13) cytokines when compared to TB infection alone." (PMID 30897083, 2019). "Moreover, MAIT cells in antibiotics-treated mice produced less interleukin (IL)-17A, and MAIT cells from FT mice proliferated more than those from antibiotics-treated mice following infection." (PMID 30487801, 2018). "IL-17A not only is essential for the defense against S. pneumoniae but also mediates the early defenses following infection by other gram-positive and gram-negative bacteria." (PMID 30214444, 2018). "During mouse infection, GC induces cytokines that indicate the presence of a T helper 17 (Th17) cell response (including the cytokine IL-17A) and not the cytokines expected from a Th1 response." (PMID 30524442, 2018). "Other cytokines (IL-12p70, IL-10, IL-17A) did not or only marginally change following infection or were even reduced (IL-23, IFNβ)." (PMID 30169526, 2018). "DN T cells have been shown to produce IL-17A earlier than CD4 T cells and demonstrate features of antigen-experienced T cells including lower threshold of stimulation, proliferation, cytokine production, and also contribute to clearance of infection." (PMID 30386336, 2018). "The RH group had lower IL-17A levels than the ME49 group at day 3 and 7 post-infection." (PMID 30564216, 2018). "In contrast, IL-17A neutralization had no significant impact on mortality or bacterial load, despite mice were challenged with higher infection dose." (PMID 30533047, 2018). "However, we observed an increased expression of IL-17A and CD40 in lung homogenates of WT in comparison with Ghrh−/− mice 48 h post-infection." (PMID 30333823, 2018). "In summary, the data suggested that the lack of IL-17A affects L3 migration into the TC and creates an environment which promotes worm development and growth at the site of infection." (PMID 29931394, 2018). "Correlating to Mtb loads, when BCG primed mice were boosted with LP-ESAT-6 subunit vaccine after infection with Mtb, there were higher levels of IFN-γ, IL-17A, and IL-22 and lower levels of IL-10 compared to BCG-vaccinated mice, demonstrating the increase in protective immunity." (PMID 30386336, 2018). "The mRNA transcript levels of IFN-γ, IP-10, and IL-17A induced by PPD-B or CE in PBMCs from M. bovis-infected calves were significantly higher than those from uninfected calves between 6 and 58 weeks post-infection." (PMID 29560355, 2018). "The reduced worm burden on days 7 and 28 p.i. concomitant with longer individual worm lengths on day 28 p.i. implies that the absence of IL-17A supports worm clearance in the early phase of infection but also promotes worm growth in the TC." (PMID 29931394, 2018). "The infection study in IL-17A–KO mice, on the other hand, revealed that absence of IL-17A marginally boosted fungal burden in the lung and accelerated the mouse death." (PMID 30409128, 2018). "IL-17A was predominantly secreted by γδT cells (especially the Vγ4+γδT subset), but not CD4+Th and CD8+Tc cells at the early stage of infection, and IL-1β and/or IL-23 were sufficient to induce IL-17A production by γδT cells." (PMID 28912779, 2017). "The Th17 and γδ T cells are major sources of IL17A and IL17F in response to infection." (PMID 28447937, 2017). "No detectable IL-10, IL-12, and IL-17A mRNA production was observed (data not shown) in any infected group, irrespective of the strain or infection dose." (PMID 28642841, 2017).